CD53 (CD53 molecule)
Description:
Structural component of specialized membrane microdomains known as tetraspanin-enriched microdomains (TERMs), which act as platforms for receptor clustering and signaling. Participates thereby in diverse biological functions such as cell signal transduction, adhesion, migration and protein trafficking. Plays a role in the activation of monocytes and B-cells. Acts as an essential regulator of B-cell development by promoting interleukin-7 receptor/IL7R signaling (By similarity). Also promotes, in B-cells, the BCR signaling by recruiting PKC to the plasma membrane in order to phosphorylate its substrates. Plays an essential role in B- and T-cells homing to lymph nodes by stabilizing L-selectin/SELL cell surface expression (By similarity). Also mediates metabolic and inflammatory functions in hepatocytes and adipose tissue by promoting TNF and LPS signaling independent of the immune compartment (By similarity).
Synonyms: MOX44; TSPAN25
Tractability: Small molecule: a structure with a bound ligand is known. Antibody: UniProt places it where antibodies can reach, with high confidence; its Gene Ontology location is reachable by antibodies, with high confidence; UniProt predicts a signal peptide or a membrane-spanning region. PROTAC: ubiquitination databases record sites on it; its protein half-life has been measured.
Gene: Protein-coding gene on chromosome 1 (110,871,176 to 110,899,936, forward strand). Ensembl gene ENSG00000143119.
Subcellular location: Cell membrane; Cell junction; Membrane; Synapse
Pathways (Reactome):
Immune System: Neutrophil degranulation
Gene Ontology:
Molecular function: identical protein binding; protein binding; protein-membrane adaptor activity
Biological process: receptor clustering; positive regulation of myoblast fusion; signal transduction
Cellular component: extracellular exosome; immunological synapse; plasma membrane; synapse; anchoring junction; cell-cell junction; specific granule membrane; tertiary granule membrane; membrane
Genetic constraint (gnomAD): Loss-of-function variants: 9 observed, 17.22 expected, observed/expected ratio (o/e) 0.52, 90% interval 0.31 to 0.91. The upper end of that interval is the gene's LOEUF score, 0.91, which puts it in group 3 of 6, group 1 being the genes least tolerant of losing a copy. Missense variants: 160 observed, 207.88 expected, observed/expected ratio (o/e) 0.77, 90% interval 0.68 to 0.88. Synonymous variants: 80 observed, 82.26 expected, observed/expected ratio (o/e) 0.97, 90% interval 0.81 to 1.17.
Homologues: Orthologues: chimpanzee CD53 (100% identical), macaque CD53 (89% identical), pig CD53 (89% identical), guinea pig CD53 (84% identical), rabbit CD53 (84% identical), mouse Cd53 (83% identical), rat Cd53 (81% identical), dog CD53 (79% identical), tropical clawed frog cd53 (55% identical), zebrafish zgc:64051 (40% identical). Paralogues in human: TSPAN9 (44% identical), TSPAN4 (39% identical), CD82 (34% identical), CD151 (30% identical), CD37 (30% identical), TSPAN33 (30% identical), TSPAN8 (30% identical), TSPAN18 (29% identical), TSPAN17 (28% identical), TSPAN5 (28% identical), CD63 (27% identical), CD81 (27% identical), and 20 more.
Diseases named in the same sentence as CD53 in open-access papers:
CD53 is named in the same sentence as 100 diseases in open-access papers, as found by Europe PMC text mining. Sharing a sentence is not in itself a finding about the gene and the disease. The quoted sentences say what the papers report.
breast carcinoma (11 papers, 2002 to 2025). "In this study, we found that the CD53 mRNA expression level was lower in metastatic OS samples, which is in accordance with the decreased CD53 expression in high-metastasis breast cancer in a previous study." (PMID 34856991, 2021). "Here, we found that it was in strong LD (r2 = 0.857) with SNP rs2885805, a functional SNP located in the enhancer region of CD53, which is a prognostic gene signature in breast cancer." (PMID 29378629, 2018). "CD53 network genes were found to be poorly expressed in the high-metastasis breast cancer transplantation model and predicted distant metastasis-free survival specifically in ER+ breast cancers." (PMID 34856991, 2021). "Other co-expressed genes such as BMF, CD53, PIK3R1, and CWF19L2 have also been reported in breast cancer studies." (PMID 40282270, 2025). "The results demonstrated that the expression levels of OLR1, ADIPOR1, CEACAM6, DNASE2, CD53, BMF, and CAMP were significantly elevated in breast cancer samples compared to healthy controls (p < 0.05)." (PMID 40282270, 2025). "CD53, absent in non-tumour ducts, was detected in 50% of breast carcinomas and, in the positive cases, a weak nuclear positivity was observed in 5–75% of neoplastic cells." (PMID 35201443, 2021).
prostate carcinoma (11 papers, 2013 to 2025). A carcinoma that arises from epithelial cells of the prostate gland. "The interplay between CD53 and other molecules like PD‐L1 may provide new insights into the complex immune evasion mechanisms and therapeutic targets in advanced prostate cancer states." (PMID 40923331, 2025).
melanoma (8 papers, 2011 to 2024). A malignant, usually aggressive tumor composed of atypical, neoplastic melanocytes. "CD2, CD8, and CD53 are mentioned together in a leukocyte infiltration score predicting melanoma patient prognosis." (PMID 38397409, 2024).
multiple myeloma (6 papers, 2016 to 2022). "Consistent with our proteomic findings, in relapsed myeloma patient tumor cells we found significant transcript decreases of CD53 and EVI2B, while MME (CD10) showed a significant increase." (PMID 35840578, 2022). "In myeloma models we identify proteins that could serve as markers of resistance to bortezomib and lenalidomide, including CD53, CD10, EVI2B, and CD33." (PMID 35840578, 2022).
ovarian carcinoma (5 papers, 2013 to 2023). A malignant neoplasm originating from the surface ovarian epithelium. "TYROBP, ITGB2, C1QB, C1QA and CD53 in module B have the top connectivity among all DEGs and are considered to have important relationship to immune response in ovarian cancer." (PMID 33987033, 2021). "CD53 was also expressed in xenografts derived from other serous ovarian cancer cell lines including CAOV3, OVMZ6, OVCAR3 and OV90 that suggests a pan-ovarian cancer association." (PMID 27140846, 2016). "Accordingly, the other four genes, namely FCGR2B, CD53, CCR1, and SLAMF8, were previously identified as integral components of a larger tumor associated macrophage-related signature with prognostic potential in patients with ovarian cancer." (PMID 37509358, 2023). "By PPI network and MCODE module, TYROBP, ITGB2, C1QB, C1QA, CD53 and CD163 have top connectivity among all DEGs and are considered to have important relationship to immune response in ovarian cancer." (PMID 33987033, 2021).
atherosclerosis (4 papers, 2020 to 2023). A disease characterized by the build-up of fatty material and calcium deposition in the arterial wall resulting in partial or complete occlusion of the arterial lumen. "Our study also found that new genes like CSF2RB, IL1RN, CCL5, MMP9, CD53, NCF2 and TLR2 associated with Inflammation present high expression both in psoriasis and atherosclerosis." (PMID 34122426, 2021). "In the atherosclerosis dataset GSE28829, CD14 (AUC = 0.938), C1QB (AUC = 0.947), CD53 (AUC = 0.952), LY96 (AUC = 0.904), P2RX7 (AUC = 0.981), C3 (AUC = 0.817), and TNFSF13B (AUC = 0.875) demonstrated favorable diagnostic efficiency for differentiating patients with atherosclerosis from controls." (PMID 37649719, 2023). "In this study, we suggested that the progression of atherosclerosis might be related to CD86, C1QB, CD53, C1QC, NCF2, and ITGAM and that it plays a role in regulating immune-competent cells such as T cell CD8 and macrophages M0 and M2." (PMID 32821283, 2020). "RBM47, HCK, CD53, TYROBP, and HAVCR2 were identified as common hub genes, which were validated to be upregulated in advanced atherosclerotic plaques, to well distinguish CAD patients from non-CAD people and to regulate immune cell function-related mechanisms in advanced atherosclerosis." (PMID 33519905, 2020).
glioma (4 papers, 1993 to 2024). A benign or malignant brain and spinal cord tumor that arises from glial cells (astrocytes, oligodendrocytes, ependymal cells). "The identification of the downstream signals of HK2 demonstrated that the high expression of hub genes, including ITGB2, CD53, C3AR1, CYBB and ITGAM, maybe a potential target for the treatment of glioma." (PMID 35982398, 2022). "Moreover, multivariate Cox regression revealed that CYBB, CD53, SCRT1 and SYP might be independent factors for predicting the prognosis of gliomas." (PMID 35982398, 2022). "Moreover, further multivariate Cox regression analysis revealed that the expression of CYBB (P = 0.00087), CD53 (P = 0.04883), SCRT1 (P = 0.00071) and SYP (P = 0.02491) can be independent factors of the prognosis of gliomas and predict the survival of glioma patients." (PMID 35982398, 2022).
lymphoma (4 papers, 1980 to 2022). A malignant (clonal) proliferation of B- lymphocytes or T- lymphocytes which involves the lymph nodes, bone marrow and/or extranodal sites. "Moreover, elevated levels of CD53 expression is found on different cancers, such as B-cell leukemia and lymphomas, suggesting it may contribute to increased survival of the tumour cells." (PMID 24832104, 2014). "Interestingly, deletion of another related tetraspanin, CD53, did not alter the metabolic phenotype of the lymphoma cells." (PMID 36100608, 2022).
Obesity (4 papers, 2019 to 2023). Accumulation of substantial excess body fat. "CD53 expression in adipose tissue correlated to levels of hepatic steatosis, as quantified by hepatic triglyceride (TG) levels in a panel of mouse strains, and is associated with adipose tissue inflammation in previous studies of obesity." (PMID 36581203, 2023). "However, the broad expression profile for CD53 and the identification of CD53 in genome-wide studies in fatty liver and obesity indicated CD53 functions that extend beyond inflammatory cell activation." (PMID 36581203, 2023). "Many studies have shown that CD53 is increased in obese and inflammatory tissues, and regulating its expression may be an effective treatment for obesity with complications." (PMID 34093637, 2021).
autoimmune disease (3 papers, 2015 to 2024). A disorder resulting from loss of function or tissue destruction of an organ or multiple organs, arising from humoral or cellular immune responses of the individual to their own tissue constituents. "It has been suggested that CD53 regulated the growth of T cells and natural killer cells and has been extensively studied in infectious diseases, autoimmune diseases, and immunodeficiency diseases." (PMID 33519905, 2020). "At least seven of these are involved in autoimmune diseases or immune cell function: Ptpn22, Adora3, Rbm15, Lrig2, Cd53, Nras, and a cluster of six chitinase-like genes." (PMID 26438525, 2015). "Additionally, we predicted and verified the STAT1 as the possible TF of the ISG15 and CD53 in the two autoimmune diseases." (PMID 39136821, 2024).
leukemia (3 papers, 2011 to 2024). A malignant (clonal) hematologic disorder, involving hematopoietic stem cells and characterized by the presence of primitive or atypical myeloid or lymphoid cells in the bone marrow and the blood. "While the occurrence of GPR56, CD53 and CD59a on leukemia cells is known, GPR56, CD53 and CD59a are highly expressed in the thymocytes of Lck-Lmo2 mice relative to wild type thymocytes and are also on the overt human tumors in addition to CD7." (PMID 30962539, 2019). "Finally, CD53 is overexpressed in Lmo2 mouse leukemias and was shown to protect human TAL1+ JURKAT cells from apoptosis." (PMID 38553571, 2024). "In this model the leukemia initiating cells (LICs) comprise pre-leukaemic, differentiation inhibited thymocytes allowing us to provide a profile of the LIC surfaceome in which GPR56, CD53 and CD59a are co-expressed with CD25." (PMID 30962539, 2019).
lung carcinoma (3 papers, 2012 to 2022). "Moreover, SASH3 is associated with gene regulatory sites (such as WAS and CD53) in lung cancer, which has diagnostic value for lung cancer metastasis." (PMID 36408131, 2022). "In conclusion, two coexpression factors (SASH3 and CD53) help classify tumor purity phenotypes and predict clinical phenotype in lung cancer with the chemokine signaling pathway." (PMID 34234827, 2021). "The intersection was taken to screen out that SASH3 and CD53 were tumor purity-related prognostic genes of lung cancer." (PMID 34234827, 2021).
asthma (2 papers, 2014 to 2016). "Although CD53 is expressed in MCs, there is only one study showing association of CD53 with asthma risk via the functional promoter polymorphism." (PMID 27243007, 2016).
atopic dermatitis (2 papers, 2014 to 2023). "The expression of the tetraspanins such as CD9, CD37, CD53, CD63, CD81, and CD82 on FcεRIpos skin dendritic cells (DCs) from atopic dermatitis patients is significantly higher when compared to skin DCs of not allergic healthy individuals." (PMID 36672710, 2023). "Interestingly, up-regulation of CD53 under inflammatory conditions is also observed on macrophages in response to lipopolysaccharide, as well as on leukocytes obtained from rheumatoid arthritis patients, patients with atopic eczema, or in lesions after spinal cord injury." (PMID 24832104, 2014).
diabetes (2 papers, 2019 to 2023). "The results of the interactions show that LAPTM5, IRF8, IGTB2, CD53, and C1QB scored higher with diabetes mellitus." (PMID 37113991, 2023).
fatty liver (2 papers, 2015 to 2023). "This CD53 inhibition directly correlates with inhibited hexose uptake and diet-induced hepatic steatosis in vivo." (PMID 36581203, 2023). "Cd53, an adipose inflammatory marker, was also highly correlated with hepatic steatosis (r = 0.58, p = 2.06 × 10−11)." (PMID 26067236, 2015).
metastatic disease (2 papers, 2014 to 2024). "Significant gene upregulation of these tetraspanins (CD53, ROM1, TSPAN3, TSPAN12, TSPAN15, and UPK1B) within immune cells in metastatic tumor suggests their potential involvement in the influence of immune responses." (PMID 38255741, 2024).
overnutrition (2 papers, 2023). An imbalanced nutritional status resulting from excessive intake of nutrients. "We used these CD53-deficient mice to define if CD53 mediates hepatic responses to chronic overnutrition." (PMID 36581203, 2023). "In particular, CD53 expression correlated with overall overnutrition or fasting-like status in the liver in mice or in isolated cultured hepatocytes." (PMID 36581203, 2023).
triple-negative breast carcinoma (2 papers, 2021 to 2023). An invasive breast carcinoma which is negative for expression of estrogen receptor (ER), progesterone receptor (PR), and human epidermal growth factor receptor 2 (HER2). "Contrastingly, there is limited information on the prognostic role of CD53 in cancer patients, with one study supporting that its upregulation may be associated with a disease-free survival benefit for patients with triple-negative breast cancer." (PMID 37509358, 2023).
Cirrhosis (1 paper, 2023). A chronic disorder of the liver in which liver tissue becomes scarred and is partially replaced by regenerative nodules and fibrotic tissue resulting in loss of liver function. "Additionally, the proportion of CD4 T cell-TNFAIP3, CD8 T cell-TNF (effector CD8 T cells), and CD8 T cell-CD53 increased, while the proportion of Treg cells decreased from HBV infection to cirrhosis." (PMID 38116005, 2023).
coeliac disease (1 paper, 2023). "For example, coeliac disease (CD) is characterized by a destruction of the intestinal epithelium driven by gluten-activated inflammation, resulting in observable villous atrophy and lymphocytic infiltration of the epithelium, as shown recently in a novel mouse model of CD53." (PMID 37002381, 2023).
diabetic nephropathy (1 paper, 2023). "Our study explored the same platform GEO dataset for diabetic nephropathy bioinformatics analysis and identified eight potential key genes (TYROBP, ITGB2, CD53, IL10RA, LAPTM5, CD48, C1QA, and IRF8), screened eight transcription factors, and identified 93 miRNA nodes." (PMID 37113991, 2023).
dyslipidemia (1 paper, 2023). "Furthermore, germline CD53 deletion in vivo blocked Western diet–induced dyslipidemia and hepatic inflammatory transcriptomic activation." (PMID 36581203, 2023).
experimental autoimmune encephalomyelitis (1 paper, 2019). An autoimmune demyelinating disease of the central nervous system that is produced experimentally in animals by the injection of homogenized brain or spinal cord in Freund's adjuvant. "Encephalitogenic T cells from Myelin Oligodendrocyte Glycoprotein (MOG)-Induced Experimental Autoimmune Encephalomyelitis (EAE) mice showed significantly lower levels of TSPAN32 and increased levels of CD9, CD53, CD82 and CD151." (PMID 31487788, 2019).
fungal infections (1 paper, 2020). "Almost three decades ago it was reported that patients who lacked CD53 suffered from an increased susceptibility to pathogens resulting in the clinical manifestation of recurrent viral, bacterial, and fungal infections." (PMID 32440787, 2020).
hepatocellular carcinoma (1 paper, 2012). A malignant tumor that arises from hepatocytes. "For example, CD53 was the most connected gene (36 co-expressions) and has been shown to be associated with metastatic spread in hepatocellular carcinoma." (PMID 22539975, 2012).
HIV-1 infection (1 paper, 2025). The type species of lentivirus and the etiologic agent of acquired immunodeficiency syndrome (AIDS). "Although CD53 gene scored the best among all the targets and was validated as a target of miR-197-3p as well, but we did not study it since detailed functional characterization of CD53 in HIV-1 infection has been already reported." (PMID 39826696, 2025). "Although CD53 showed the highest score and was validated as a target of miR-197-3p, we did not select it for our study as its role in HIV-1 infection is already well characterized." (PMID 39826696, 2025).
Hyperglycemia (1 paper, 2022). An increased concentration of glucose in the blood. "In this study, we showed that CD53 expression is minimal in control samples, in which the lack in CD53 has significantly decreased the risk of hyperglycemia, proteinuria, and inflammatory response." (PMID 35909518, 2022).
hypertriglyceridemia (1 paper, 2023). A laboratory test result indicating elevated triglyceride concentration in the blood. "Second, CD53 ablation blocked diet-induced liver lipid and glucose homeostatic perturbations in NASH-inducing contexts but not in the setting of high-fat (western style) dietary feeding alone (although it is noted that CD53 KO mice were protected from WD-induced hypertriglyceridemia)." (PMID 36581203, 2023).
Insulin resistance (1 paper, 2023). Increased resistance towards insulin, that is, diminished effectiveness of insulin in reducing blood glucose levels. "Together, these data prompted the hypothesis that CD53 moderates both inflammatory and metabolic functions under duress to promote inflammatory metabolic diseases, such as insulin resistance, visceral adipose inflammation, and hepatic lipid accumulation." (PMID 36581203, 2023). "Yet, whether CD53 mechanistically participates in the adaptive metabolic effects, which we previously demonstrated in GLUT8-deficient mice (e.g., protection from NAFLD and insulin resistance), remains to be fully determined." (PMID 36581203, 2023).
lung adenocarcinoma (1 paper, 2024). A carcinoma that arises from the lung and is characterized by the presence of malignant glandular epithelial cells. "Also the high expression of SNX20, which is connected with SASH3 and CD53 through the focal adhesion-encoding gene LPXN, has been associated with immune-active TIME and better OS in lung adenocarcinoma patients." (PMID 39107857, 2024).